IGF2BP1 (insulin like growth factor 2 mRNA binding protein 1)
Diseases named in the same sentence as IGF2BP1 in open-access papers (continued):
Sharing a sentence is not in itself a finding about the gene and the disease.
lung adenocarcinoma (25 papers, 2020 to 2026). A carcinoma that arises from the lung and is characterized by the presence of malignant glandular epithelial cells. "CDCA4 interacts with IGF2BP1 to regulate lung adenocarcinoma proliferation via the PI3K/AKT pathway." (PMID 39969065, 2025). "Previous work demonstrated the involvement of Igf2bp1 in helping mediate cell migration in lung adenocarcinoma cells, both in cultured cells and in mice." (PMID 34895045, 2022). "Another example was that LIN28B-AS1 accelerated the proliferation and metastasis of lung adenocarcinoma cells by binding to IGF2BP1 protein." (PMID 35945579, 2022). "For instance, a novel circular RNA, circXPO1, promotes lung adenocarcinoma progression by interacting with IGF2BP1, and hot-star circRNA CDR1as and CircRNA0001859 are key players in balancing cardiovascular–pulmonary homeostasis." (PMID 34858969, 2021). "Further studies demonstrated that IGF2BP1 expression was strongly associated with immune infiltration, immune checkpoint expression, the effectiveness of immunotherapy in LUAD patients, and the incidence, progression, metastasis, and treatment resistance of lung adenocarcinoma." (PMID 41809822, 2026). "We have focused on the involvement of IGF2BP1 in lung adenocarcinoma (LUAD), where we have observed that IGF2BP1 synergizes with mutant Kras to accelerate tumor progression." (PMID 40629079, 2025). "Similarly, analysis of IGF2BP1 expression in clinical patients confirmed that elevated IGF2BP1 expression could enhance lymph node metastasis and recurrence and accompany poor prognosis in lung adenocarcinoma and HCC patients." (PMID 40584294, 2025). "This is particularly evident in lung adenocarcinoma and squamous cell carcinoma, where GAPDH expression shows the strongest correlation with the m6A reader protein IGF2BP1." (PMID 38928396, 2024). "In conclusion, we identified GULPsig, consisting of IGF2BP1, IGF2BP3, SMC1B, CLDN6, and LY6K, as a potential prognostic signature for lung adenocarcinoma patients." (PMID 37655157, 2023). "It has shown that IGF2BP1 is overexpressed in NSCLC and significant negatively related to survival in lung adenocarcinoma in both in vivo and in vitro studies." (PMID 35903696, 2022). "Notably, a previous study revealed that circXPO1 binds with IGF2BP1 to raise catenin beta 1 (CTNNB1) mRNA stability, thereby promoting lung adenocarcinoma progression." (PMID 37370759, 2023). "Moreover, high expression level of IGF2BP1 and IGF2BP3 has been detected in many human cancers, including glioma and lung adenocarcinoma." (PMID 36761737, 2023). "For instance, IGF2BP1 and IGF2BP3 showed an oncogenic role in KIRC and lung adenocarcinoma (LUAD)." (PMID 33718187, 2021). "The results revealed that the levels of IGF2BP1, particularly IGF2BP2 and IGF2BP3, were remarkably upregulated in many cancer types such as bladder urothelial carcinoma (BLCA), liver hepatocellular carcinoma (LIHC), lung adenocarcinoma (LUAD), and lung squamous cell carcinoma (LUSC)." (PMID 35003212, 2021).
bladder cancer (24 papers, 2017 to 2025). "For instance, IGF2BP1 enhances mRNA stability and has been demonstrated to combine with circPTPRA in the cytoplasm of bladder cancer cells; additionally, the upregulation of LRPPRC is closely related to prognosis, survival and resistance in prostate cancer." (PMID 39779466, 2025). "For example, in bladder cancer, IGF2BP1 recognizes the m6A moiety in the vicinity of the PD-L1 stop codon, enhancing mRNA stability to induce immune escape via a METTL3-mediated m6A mechanism." (PMID 37554271, 2023). "Abnormally expressed circ-PTPRA eliminated the enhancement of the malignant cell phenotype mediated by IGF2BP1 in bladder cancer." (PMID 37304234, 2023). "IGF2BP1 was positively correlated with tumor size, lymph node metastasis, and late clinical-stage of bladder cancer." (PMID 37701836, 2023). "circPTPRA was shown to suppress the progression of bladder cancer, through its interaction with IGF2BP1, an N6-methyladenosine (m6A) reader, and blocking the IGF2BP1-mediated recognition of m6A-modified RNAs." (PMID 36104321, 2022). "For example, circPTPRA suppresses bladder cancer progression by blocking the interaction between IGF2BP1 and its target mRNAs." (PMID 36224588, 2022). "In bladder cancer cell lines, we show that circCDYL interacts with IGF2BP1 and IGF2BP2 and that depletion of circCDYL or these RBPs disturb several hallmarks of cancer." (PMID 33287884, 2020). "Interestingly, circPTPRA is a tumor suppressor ncRNA in bladder cancer which interacts with KH domains of IGF2BP1 to endogenously block the recognition of IGF2BP1 to m6A-modified RNAs including FSCN1 and Myc." (PMID 38075202, 2024). "METTL14, YTHDC1, and WTAP may be protective factors for bladder cancer, the higher expressions were related to the longer overall survival of patients, while IGF2BP1-3, YTHDF1, LRPPRC, ALKBH5, and FTO were risk factors for bladder cancer." (PMID 37701836, 2023). "Moreover, IGF2BP1 elevates the stability and expression of PD-L1, mediating the immune evasion of bladder cancer." (PMID 37554271, 2023). "However, several studies have reported that circPTPRA upregulates KLF9 by sponging miR‐636 or interacting with IGF2BP1 to inhibit the progression of bladder cancer." (PMID 37041721, 2023). "Likewise, IGF2BP1 also binds to the 3′ UTR of PKM2 to induce the Warburg effect in bladder cancer." (PMID 37554271, 2023). "The expressions of IGF2BP1, IGF2BP3, YTHDF1, YTHDF2, and HNRNPC were significantly up-regulated in bladder cancer." (PMID 40083693, 2025). "(A) Relative enrichment of circHIPK3 levels or ACTB mRNA between IP and input for the three RNA-binding proteins (RBPs) GRWD1, IGF2BP1, and IGF2BP2 in the bladder cancer cell line FL3." (PMID 39041323, 2024). "It was found in humans and animal models that METTL3, FTO, IGF2BP1, IGF2BP3, YTHDF1, YTHDF 2, ELAV-like protein 1 (ELAVL1), HNRNPA2B1 were upregulated in bladder cancer cells." (PMID 37701836, 2023). "Research has shown that circFAM13B competes with PKM2 to bind to the KH3-4 domain of IGF2BP1, leading to the attenuation of PKM2 expression in bladder cancer." (PMID 37554271, 2023). "Consistent with our observations in HepG2, circCDYL is much higher expressed than the mRNAs of its interacting RBPs, IGF2BP1 (> 180×) and IGF2BP2 (> 5×), in both bladder cancer cell lines, supporting circCDYL’s potential to act as a sponge." (PMID 33287884, 2020). "IGF2BP1 could function as an m6A reader and enrich the 3'-UTR of immune checkpoint PD-L1 mRNA, thus enhancing the mRNA stability of PD-L1 in bladder cancer." (PMID 36966311, 2023). "In preliminary studies, we found that the expression levels of the classic proto-oncogenes, IGF2BP1, MYC, LIN28B and STAT3 in bladder cancer T24 cells were higher than those in normal cells, while the expression levels of the tumor suppressor genes FTO and TIA1 were negligible in T24 cells." (PMID 35288535, 2022).
leukemia (22 papers, 2018 to 2025). A malignant (clonal) hematologic disorder, involving hematopoietic stem cells and characterized by the presence of primitive or atypical myeloid or lymphoid cells in the bone marrow and the blood. ",112,114, 115, 116, 117,168 IGF2BP1 promotes the self-renewal and initiation of leukemia stem cells as well as the sensitivity of leukemia cells to the alkylating agents by regulating the expression of ALDH1A1, HOXB4, and MYB." (PMID 40584294, 2025). "The IGF2BP1 inhibitor BTYNB has been shown to effectively repress the progression of leukemia cells, suggesting potential applicability to other tumors." (PMID 39342091, 2024). "Restricting IGF2BP1 expression resulted in increased sensitivity of leukemia cells to doxorubicin, cytarabine, and cyclophosphamide, showing promising potential for chemoresistance therapy." (PMID 38328550, 2024). "IGF2BP1 and IGF2BP3 have been linked to leukemia, as well as solid malignancies, and are often co-expressed with LIN28B." (PMID 38601080, 2024). "It has been observed that IGF2BP1 is widely overexpressed in advanced leukemia and can inhibit the differentiation of cancer stem cells." (PMID 39342091, 2024). "In leukemia, IGF2BP1 increases the stemness of leukemia cells by positively regulating the hematopoietic stem cell regulators HOXB4 and MYB, as well as the stem cell marker ALDH1A1." (PMID 38328550, 2024). "MYB promoted leukemia stem cell phenotype via interaction with the insulin-like growth factor 2 mRNA-binding protein 1 (IGF2BP1), and IGF2BP1 knockdown sensitized leukemia cells to the DNA-targeting drugs doxorubicin, cyclophosphamide, and cytarabine." (PMID 38835346, 2024). "It is noteworthy that the tumorigenic driving effect of IGF2BP1 in leukemia is predominantly regulated through non-m6A-dependent mechanism, according to a large number of papers related to hematologic tumors." (PMID 39342091, 2024). "Overall, our results suggest that IGF2BP1 plays an important role in the pathogenesis of ETV6::RUNX1 leukemia through multiple oncogenic pathways and can be utilized as an ideal therapeutic target for this particular subtype." (PMID 37670323, 2023). "These pathways were also specifically enriched in the transcriptome of ETV6::RUNX1 positive patients indicating a critical role for IGF2BP1 in this leukemia subtype." (PMID 37670323, 2023). "To study the pathogenetic role of IGF2BP1 in leukemia development, we developed the first in-vivo model with enforced expression of IGF2BP1 in the hematopoietic system." (PMID 37670323, 2023). "IGF2BP1 depletion can reduce colony formation, impede leukemogenesis and proliferation, and postpone leukemia cell development in NSG mice." (PMID 35720276, 2022). "Insulin-like growth factor 2 mRNA binding protein 1 (IGF2BP1) is a carcinoembryonic protein that is expressed in various cancers including leukemia." (PMID 34676171, 2021). "Knockdown of another m6A binding protein, IGF2BP1, significantly inhibits colony formation, reduces leukemia cell proliferation, enhances myeloid differentiation and delays leukemia development in immunodeficient recipient mice." (PMID 34001273, 2021). "Upregulation of IGF2BP1 increases the resistance of leukemia cells to chemotherapeutic drugs by enhancing the expression of ALDH1A1, HOXB4, and MYB through posttranscriptional regulation." (PMID 34001273, 2021). "IGF2BP1 leads to increased proliferation and tumorigenesis because leukemia cell lines, with low expression of IGF2BP1, have a lower ability to form colonies and initiate tumors." (PMID 32408494, 2020). "Knockdown of MYB-regulated IGF2BP1 enhanced differentiation of leukemia cells by ATRA." (PMID 38835346, 2024). "In addition, it was found that BTYNB induced the S phase arrest and facilitated the apoptosis and differentiation of leukemia cells by blocking IGF2BP1 expression, ultimately slowing down the progression of leukemia." (PMID 39342091, 2024).
leukemia (continued). "Therefore, IGF2BP1 plays a role in maintaining the properties of leukemia stem cells by regulating transcriptional and metabolic pathways." (PMID 39342091, 2024). "The enforced expression of IGF2BP1 in leukemia cells led to doxorubicin resistance." (PMID 38835346, 2024). "IGF2BP1 inhibition also facilitated the sensitivity of leukemia cells to chemotherapy drugs." (PMID 39342091, 2024). "Whether IGF2BP1 regulation of leukemia is dependent on m6A modification remains unclear and warrants further investigation." (PMID 39342091, 2024). "The IGF2BP1 protein is expressed in a number of different types of cancer, including leukemia." (PMID 35743641, 2022). "The expression level of IGF2BP1 in ETV6-RUNX1-positive B-cell acute lymphoblastic leukemia cells was investigated, revealing a significant up-regulation of this gene in the leukemia cells." (PMID 40584293, 2025). "Fetal-specific genes (HMGA2) have been identified in a rare HSC-like fraction of KMT2A-r infant leukemia, and IGF2BP1 maintains LSC by regulating HOXB4, MYB, and ALDH1A1 in pediatric leukemia cell lines." (PMID 38601080, 2024). "With many of these pathways being druggable and a small molecule inhibitor for IGF2BP1 available, our work lays the foundation for novel combinatorial therapeutic approaches in ETV6::RUNX1 positive leukemias." (PMID 37670323, 2023). "IGF2BP1 expressed in AML cells promotes leukemogenesis and proliferation and maintains the stemness of leukemia cells by regulating HOXB4, MYB, and ALDH1A1, which are LSC phenotype-associated transcriptional and metabolic factors." (PMID 35720276, 2022). "We have investigated the utility of studying the expression of IGF2BP1, an RNA binding protein known to be overexpressed in ETV6-RUNX1 leukemia, by qPCR, to be used as a cheaper and quicker alternative to diagnose the presence of the translocation." (PMID 33708624, 2021). "Furthermore, knockdown experiments targeting either IGF2BP1 or ETV6-RUNX1 led to a reduction in the proliferative capacity and an increase in apoptosis of the leukemia cells." (PMID 40584293, 2025). "Our previous study of leukemia stem cells (LSC) properties (e.g., tumorigenicity, clonogenicity, and expression of aldehyde dehydrogenase (ALDH) by ALDEFLUORTM analysis) established IGF2BP1 as an important regulator of the leukemia stem cell phenotype." (PMID 37503349, 2023). "Among them, IGF2BP-1 has been reported to inhibit IGF-II mRNA translation during development while on the other hand IGF2BP-2 and -3 were previously shown to promote IGF-II mRNA translation in rhabdomyosarcoma and leukemia respectively." (PMID 30733684, 2018). "Interestingly, induced expression of structurally and functionally related paralogs Igf2bp1 and Igf2bp2 was noted with enforced expression of non-MLL-Af4 oncogenic drivers, again in concordance with observations in human leukemia." (PMID 34321607, 2022).
osteosarcoma (21 papers, 2013 to 2025). A usually aggressive malignant bone-forming mesenchymal neoplasm, predominantly affecting adolescents and young adults. "Moreover, the significant associations of IGF2BP1 overexpression with advanced clinicopathological characteristics and poor prognosis in osteosarcoma patients were also determined." (PMID 30220021, 2019). "Moreover, the miR-150-low/IGF2BP1-high expression was significantly associated with high tumor grade (P = 0.01), positive metastasis (P < 0.001) and recurrence (P < 0.001), and poor response to chemotherapy (P = 0.001) of patients with osteosarcomas." (PMID 30220021, 2019). "IGF2BP1 mediates the mRNA stabilization of ERRα in an m6A-dependent way in osteosarcoma, thus increasing its expression level." (PMID 40584294, 2025). "For example, IGF2BP1-stabilized estrogen-related receptor alpha (ERRα) mRNA is involved in metabolic reprogramming of chemoresistant osteosarcoma cells." (PMID 40592832, 2025). "The RBM47 and IGF2BP1 mediated circular FNDC3B/FNDC3B mRNA imbalance was involved in the malignant processes of osteosarcoma in vitro and in vivo." (PMID 38129874, 2023). "Consistently, our data here confirmed the decreased expression of IGF2BP1 at both mRNA and protein levels and also shown its cytoplasmic localization in malignant cells of osteosarcoma tissues." (PMID 30220021, 2019). "More importantly, both overall and disease-free survivals of osteosarcoma patients with miR-150-low/IGF2BP1-high were shortest, compared to miR-150-low/IGF2BP1-low, miR-150-high/IGF2BP1-high, miR-150-high/IGF2BP1-low groups (both P < 0.001)." (PMID 30220021, 2019). "Especially, IGF2BP1 mRNA expression was inversely correlated with the level of miR-150 in osteosarcoma tissues, and the downregulation of endogenous IGF2BP1 exhibited similar effects of overexpression of miR-150 in this malignancy." (PMID 30220021, 2019). "According to the observation of immunochemistry, the positive immunostaining of IGF2BP1 protein was predominantly localized in cytoplasm of tumor cells in primary osteosarcoma tissues." (PMID 30220021, 2019). "Then, subcellular localization and expression pattern of IGF2BP1 protein in 100 osteosarcoma tissues were examined by immunohistochemistry." (PMID 30220021, 2019). "Osteosarcoma patients with miR-150-low expression or IGF2BP1-high expression more frequently had high tumor grade (both P = 0.02), positive metastasis (both P = 0.001) and recurrence (both P = 0.001), and poor response to chemotherapy (both P = 0.01)." (PMID 30220021, 2019). "In the present hospital-based case study, we investigated the clinical relevance of miR-150 and its target gene IGF2BP1 in human osteosarcoma for the first time." (PMID 30220021, 2019). "Immunostaining of IGF2BP1 protein was localized in cytoplasm of tumor cells in osteosarcoma tissues." (PMID 30220021, 2019). "Then, the subcellular localization and expression pattern of IGF2BP1 protein were examined by immunohistochemistry using 100 osteosarcoma tissues." (PMID 30220021, 2019). "Kaplan–Meier and log-rank tests showed that osteosarcoma patients with miR-150-low or IGF2BP1-high expression had shorter overall and disease-free survivals than those with miR-150-high or IGF2BP1-low expression (all P < 0.001)." (PMID 30220021, 2019). "In vitro assays showed that IGF2BP1 downregulation by another microRNA (miR-150) reduced migration and invasion of an osteosarcoma cell line." (PMID 30558204, 2018). "Of relevance, a similar role for Staufen1 in regulating c-myc expression was reported in a study focused on IGF2BP1 in osteosarcoma U2OS cells." (PMID 28211476, 2017). "In osteosarcoma-derived U2OS cells, knockdown of IGF2BP1 induced a severe loss of stress fibers and an increase in the number of needle-like F-actin structures thus impairing cell migration." (PMID 25889892, 2015).